BGN (biglycan)
Diseases named in the same sentence as BGN in open-access papers (continued):
Sharing a sentence is not in itself a finding about the gene and the disease.
lymph node metastasis (5 papers, 2014 to 2023). "In GC, it has been shown that patients with high biglycan levels are associated with high tumor stages, vessel invasion, the presence of lymph node metastasis, and poor overall survival." (PMID 33809543, 2021). "In colorectal cancer, high levels of biglycan have been associated with cancer aggressiveness, including tumor advanced stage, lymph node metastasis, and worse overall patient survival." (PMID 33809543, 2021). "Importantly, high expression of BGN correlated significantly with T stage, LNM (lymph node metastasis), poor tumor differentiation degrees, advanced tumor-node-metastasis (TNM) stage, and postoperative PM (P < 0.05, respectively)." (PMID 36632455, 2023).
osteoporosis (5 papers, 2012 to 2022). A condition of reduced bone mass, with decreased cortical thickness and a decrease in the number and size of the trabeculae of cancellous bone (but normal chemical composition), resulting in increased fracture incidence. "By the observation that biglycan-deficient mice display an osteoporosis-likephenotype, biglycan was discovered to be the first non-collageneous matrix component foundin bone, being a regulator of bone formation and mass." (PMID 22821552, 2012). "In biglycan/decorin-deficient animals, the early death of osteogenic stem cells and osteoblast precursors resulted in a reduction in the number of mature osteoblasts, contributing to reduced osteogenesis and an osteoporosis-like phenotype." (PMID 35466193, 2022). "Osteoporosis-like phenotype andabnormalities of collagen fibrils observed in biglycan-deficient mice initiated a number ofinvestigations addressing the mechanisms of biglycan-dependent regulation of bone formationand collagen fiber assembly." (PMID 22821552, 2012). "Due to a reduction in bone production, mice with a targeted disruption of biglycan develop age-dependent osteoporosis, with smaller trabecular volume and thinner cortices than their wild-type counterparts." (PMID 35466193, 2022). "One of these was biglycan, a bone modifying protein in murine osteoporosis and collagen 1a2, the most abundant protein in bone matrix." (PMID 34581667, 2021).
breast tumors (4 papers, 2022 to 2024). "BGN expression was significantly downregulated in patient brain metastases as compared to the matched primary breast tumors and BGN overexpression in cancer cells inhibited their growth in vitro and in vivo." (PMID 37456245, 2023). "This revealed a significant downregulation of BGN in brain metastases as compared to the patient-matched primary breast tumors." (PMID 37456245, 2023). "We found that BGN mRNA expression was significantly higher in breast tumors as compared to normal breast tissue samples." (PMID 35053617, 2022).
endometriosis (4 papers, 2014 to 2026). The growth of functional endometrial tissue in anatomic sites outside the uterine body. "Previously, upregulated BGN associated with estrogen metabolism and action in endometriosis was confirmed through immunohistochemical staining." (PMID 36059959, 2022). "Through the Lasso approach, we determined four characteristic genes among endometriosis-related genes, containing BGN, AQP1, ELMO1 and DDR2." (PMID 36059959, 2022). "Through Lasso algorithm, four characteristic genes were determined among the shared endometriosis-related genes, containing BGN, AQP1, ELMO1, and DDR2." (PMID 36059959, 2022). "Altogether, our research determined four characteristic genes (BGN, AQP1, ELMO1, and DDR2) with the favorable efficacy in diagnosing endometriosis." (PMID 36059959, 2022). "In the two datasets, higher levels of BGN, AQP1, ELMO1, and DDR2 were confirmed in endometriosis than normal endometrium tissues." (PMID 36059959, 2022). "The AUCs (95%CI) of AQP1, BGN, DDR2, and ELMO1 were 0.96 (1.00–0.89), 0.98 (1.00–0.95), 1.00 (1.00–0.99), and 0.99 (1.00–0.98), respectively, demonstrating that each characteristic gene enabled to diagnose endometriosis accurately and sensitively." (PMID 36059959, 2022).
glioma (4 papers, 2020 to 2024). A benign or malignant brain and spinal cord tumor that arises from glial cells (astrocytes, oligodendrocytes, ependymal cells). "Finally, functional experiments were performed to evaluate the roles of risk genes in the cell viability of glioma cells, which demonstrated that silencing BGN, SDC1, SERPINA1, TUBA1C, C1GALT1C1L and SPTBN5 could inhibit the growth and viability of glioma cells." (PMID 38396140, 2024). "Similarity, both the mRNA level and protein level of WISP1 decreased in BGN KD glioma cells." (PMID 33117706, 2020). "To explore whether BGN and WISP1 act in concert in GBM through their positive feedback loop, we determined the expression correlation between BGN and WISP1 by qPCR and Western-blotting analyses, and found both the mRNA and protein levels of BGN decreased in WISP1 KD glioma cells." (PMID 33117706, 2020). "Moreover, functional experiments were performed to evaluate the roles of risk genes in the cell viability and cell number of glioma U87 and U251 cells, which demonstrated that silencing BGN, SDC1, SERPINA1, TUBA1C, C1GALT1C1L and SPTBN5 could inhibit the growth and viability of glioma cells." (PMID 38396140, 2024).
hepatocellular carcinoma (4 papers, 2016 to 2024). A malignant tumor that arises from hepatocytes. "Co-treatment with KPA also decreased the expression of genes, regulating the progression of fibrosis (e.g., COL6A3, AEBP1, SPARC, TNC, LAMB1, BGN) and hepatocellular carcinoma (e.g., COL4A1, COL4A2, TUFT1, VCAN, NID1)." (PMID 39404414, 2024). "Specific extracellular matrix proteoglycans, such as versican, aggrecan, biglycan, and decorin, which are increased in rat hepatocellular carcinomas, may affect binding with the C4S attachments on the proteoglycan." (PMID 27078017, 2016). "In addition, high plasma concentrations of biglycan were observed in patients with colorectal and hepatocellular carcinomas with the highest concentrations in those with metastatic lesions." (PMID 27295191, 2016).
keloid (4 papers, 2019 to 2025). An irregularly shaped, elevated mark on the skin caused by deposits of excessive amounts of collagen during wound healing. "Some proteoglycans such as biglycan and decorin are aberrantly produced in keloids, leading to an abnormal collagen architecture." (PMID 39373734, 2025). "Interestingly, basic fibroblast growth factor (bFGF) can up-regulate BGN while suppressing DCN expression in keloid fibroblasts." (PMID 32063855, 2019). "Moreover, BGN transcription was up-regulated in keloid tissues." (PMID 32063855, 2019). "The results showed that the expression of 12 genes (Hub genes) significantly increased in the development of keloid (P < 0.05) while that of TGFB3, SOX9, and BGN did not change significantly (P > 0.05)." (PMID 35872873, 2022).
lupus nephritis (4 papers, 2012 to 2024). Glomerulonephritis in the context of systemic lupus erythematosus. "In patients with lupus nephritis (LN) and in lupus-prone mice, enhancedplasma levels of biglycan correlate with the abundance of circulating CXCL13 and theextent of albuminuria." (PMID 22821552, 2012). "Plasma biglycan levels increased in patients with diabetic nephropathy, lupus nephritis, and in those with acute renal allograft rejection, and correlated with increased levels of the pro‐inflammatory chemokines/cytokines RANTES, IL‐1β, TNF‐α, MCP‐1 and CXCL13." (PMID 39600538, 2024). "Another study suggested that down-regulation of BGN levels in models such as unilateral ureteral obstruction and lupus nephritis effectively reduces the expression levels of nucleotide-binding oligomerisation domain-like receptor protein 3 (NLRP3) and caspase-1 activity." (PMID 35069594, 2021). "The biglycan-induced inflammasome activation was found to be of considerable relevance invivo in two mouse models of sterile renal inflammation (UUO and Murphy Roths Large[MRL]/lpr lupus nephritis) and in the prototypic pathogen-mediatedsystemic inflammation of LPS-induced sepsis." (PMID 22821552, 2012).
ovarian cancer (4 papers, 2015 to 2024). A primary or metastatic malignant neoplasm involving the ovary. "In this study, we found that PDK1 interacts with BGN and positively regulates BGN expression by modulating BGN protein stability in ovarian cancer cells." (PMID 39578715, 2024).
triple-negative breast carcinoma (4 papers, 2019 to 2024). An invasive breast carcinoma which is negative for expression of estrogen receptor (ER), progesterone receptor (PR), and human epidermal growth factor receptor 2 (HER2). "Further, in pan-cancer analysis, BGN was also an unfavorable predictor of overall survival and response to immunotherapy in patients with multiple malignancies besides triple-negative breast cancer." (PMID 39418248, 2024). "Although decorin is regarded as the “endogenous guardian” and biglycan acts as a danger signal in cancer, asporin acts as an oncogene in some types of cancer (breast, pancreatic, colorectal, gastric, and prostate), but as a tumor suppressor gene in triple-negative breast cancer." (PMID 31608236, 2019). "Recently, a team in our country has found that biglycan (BGN), an extracellular protein, is a specific factor secreted by CAFS and a prognostic marker and immunotherapy target of triple-negative breast cancer." (PMID 39418248, 2024).
Ureteral obstruction (4 papers, 2012 to 2021). Obstruction of the flow of urine through the ureter. "Specifically, in the unilateral ureteral obstruction (UUO) model, tubular biglycan up-regulation was observed before macrophage infiltration, indicating that biglycan could act as an initiator and regulator of inflammation in the kidney." (PMID 24678881, 2014). "In a murine model of unilateral ureteral obstruction (UUO),the upregulation of biglycan in the renal interstitium was followed by macrophageinfiltration, indicating that biglycan might influence the initiation of renal inflammation." (PMID 22821552, 2012).
Autoimmunity (3 papers, 2012 to 2023). The occurrence of an immune reaction against the organism's own cells or tissues. "The ECM components biglycan (Bgn) and decorin (Dcn) mediate sterile inflammation and both are implicated in autoimmunity." (PMID 34381449, 2021). "At the earliest timepoints, we found autoantibodies targeting several innate immune ligands including citrullinated histones, fibrinogen, and biglycan, thus providing insights into the earliest autoantigen targets and potential mechanisms underlying the onset and development of autoimmunity in RA." (PMID 22662108, 2012). "For example, small proteoglycans (biglycan [Bgn] and decorin [Dcn]) in the SG ECM are mediators of sterile inflammation and implicated in autoimmunity." (PMID 37165024, 2023).
diabetic nephropathy (3 papers, 2017 to 2025). "Even though, there are no data addressing biglycan and sphingolipid interaction directly, SphKs and S1P have been studied in several renal diseases associated with overexpression of biglycan, namely diabetic nephropathy, glomerulonephritis, fibrosis, nephroblastoma and acute kidney injury." (PMID 28282921, 2017).
emphysema (3 papers, 2008 to 2022). "Decreased decorin and biglycan expressions have also been shown in peribronchiolar areas in patients with severe pulmonary emphysema." (PMID 23406566, 2013).
Hyperglycemia (3 papers, 2013 to 2023). An increased concentration of glucose in the blood. "Hyperglycemia induces overexpression of endogenous TLR4 ligands, fibronectin, and biglycan." (PMID 23149823, 2013).
Meester-Loeys syndrome (3 papers, 2017 to 2024). "Defects in the core proteins of DS-PGs such as decorin and biglycan cause congenital stromal dystrophy of the cornea, spondyloepimetaphyseal dysplasia, and Meester-Loeys syndrome." (PMID 28346368, 2017). "These knockout mice may become models for spondyloepimetaphyseal dysplasia and Meester-Loeys syndrome in human BGN deficiencies, and may be helpful for developing therapeutic agents for these disorders." (PMID 28346368, 2017). "Pathogenic loss-of-function variants in BGN, an X-linked gene encoding biglycan, are associated with Meester-Loeys syndrome (MRLS), a thoracic aortic aneurysm/dissection syndrome." (PMID 38531898, 2024). "Meester-Loeys syndrome (MRLS, MIM #300989) is an X-linked thoracic aortic aneurysm and dissection (TAAD) syndrome caused by loss-of-function variants in the biglycan gene (BGN)." (PMID 38531898, 2024).
myocardial ischemia (3 papers, 2015 to 2024). A disorder of cardiac function caused by insufficient blood flow to the muscle tissue of the heart. "Both BGN and DCN have been shown to act on Toll-like receptors (TLR), which have been implicated in their protective effect against cardiac ischemia as well as in their ability to upregulate tumor suppressor genes facilitating DNA repair mechanisms." (PMID 38786104, 2024). "In our setup, following myocardial ischemia biglycan, decorin and Timp1 mRNA levels are increased in BC−/EC+." (PMID 25875863, 2015).
renal cell carcinoma (3 papers, 2012 to 2025). "To analyse biglycan expression in human TECs and NECs, we isolated TECs from human renal cell carcinoma tissue and NECs from normal renal tissue in the same patients." (PMID 22374465, 2012). "Moreover, BGN expression has potential usefulness for the development of ST-EPN therapy because inhibition of renal cell carcinoma growth has been promoted by biglycan siRNA-containing nanodevices in vivo models." (PMID 39762990, 2025). "Therapies targeting these components could therefore prove beneficial, for example, it has been shown that Biglycan inhibition, through a nanodevice encapsulating a siRNA delivery system, significantly impairs tumor growth of xenografted renal cell carcinoma in nude mice." (PMID 39155517, 2025).
spondyloepimetaphyseal dysplasia (3 papers, 2017 to 2024). An osteochondrodysplasia that results in abnormalities of bone growth in the vertebral column, epiphysis, and metaphysis. "Interestingly, both biglycan and aggrecan, two proteoglycans altered in MSS, have been associated with spondyloepimetaphyseal dysplasia, spondyloepiphyseal dysplasia, and chondrodysplastic dwarfism." (PMID 39180052, 2024).
stomach cancer (3 papers, 2010 to 2024). "Biglycan was often observed in the cancer cell cytoplasm and in the stroma of gastric tumors." (PMID 33809543, 2021). "At the protein level, we found that biglycan is mostly absent in normal gastric glands being overexpressed in metaplasia and gastric tumor tissues." (PMID 33809543, 2021).
systemic lupus erythematosus (3 papers, 2013 to 2020). An autoimmune multi-organ disease typically associated with vasculopathy and autoantibody production. "A recent report has demonstrated a role for biglycan in MRLlpr lupus." (PMID 24086313, 2013). "Thus, soluble biglycan in inflammatory renal diseases, HMGB1 in systemic lupus erythematosus, or S100 proteins in several inflammatory conditions are some examples." (PMID 33537330, 2020).
thoracic aortic aneurysm (3 papers, 2023 to 2025). An aneurysm formed in the wall of the proximal portion of the descending aorta proceeding from the arch of the aorta. "For example, biglycan deficiency/mutation cause spontaneous aortic dissection and rupture in mice and thoracic aortic aneurysms and dissections in humans." (PMID 37079653, 2023).
type 2 diabetes (3 papers, 2016 to 2024). "Furthermore, we observed that adipose tissue biglycan mRNA expression was not increased by the presence of type 2 diabetes in either obese or normal-weight subjects." (PMID 27465988, 2016). "On the other hand, in obese patients, regardless of the presence of type 2 diabetes, both VAT and SAT biglycan mRNA levels were significantly higher (3–4-fold) than in normal-weight control subjects." (PMID 27465988, 2016). "To determine the location of biglycan in adipose tissues, we performed IHC on VAT and SAT samples from obese women with or without type 2 diabetes and normal-weight women." (PMID 27465988, 2016). "We compared biglycan expression levels in two separate fat depots, abdominal subcutaneous adipose tissue (SAT) and visceral adipose tissue (VAT), in obese women (with or without type 2 diabetes) and normal-weight women." (PMID 27465988, 2016).
urothelial carcinoma (3 papers, 2013 to 2021). A malignant neoplasm derived from the transitional epithelium of the urinary tract (urinary bladder, ureter, urethra, or renal pelvis). "Invitro knock-down of endogenous biglycan in human urothelial carcinoma cells (J82 cells) increased proliferation, whereas addition of recombinant biglycan and overexpression of biglycan inhibited tumor cell proliferation." (PMID 24223213, 2013).
aneurysm (2 papers, 2022 to 2024). Bulging or ballooning in an area of an artery secondary to arterial wall weakening. "Another study discovered biglycan deficiency results in disruption to collagen fibres and up-regulation of vascular perlecan content with an associated increase in aneurysm development in mice." (PMID 36012466, 2022). "An increase in RNA levels of versican but not biglycan was also observed in aneurysm patients compared to control." (PMID 36012466, 2022).
aortic aneurysm (2 papers, 2021 to 2024). A ruptured aneurysm located in the wall of the proximal portion of the descending aorta proceeding from the arch of the aorta. "For example, loss of biglycan (BGN), a member of SLRP family, involves in aortic rupture, aortic aneurysm (AA), and AD observed in BGN-knockout (KO) mice and patients with loss-of-function mutations in BGN." (PMID 34310653, 2021). "The clinical phenotype of female BGN variant carriers ranged from no phenotype to aortic aneurysm with typical MRLS connective tissue features." (PMID 38531898, 2024).
cervical cancer (2 papers, 2016 to 2019). A primary or metastatic malignant neoplasm involving the cervix. "Western blot analysis confirmed that LYZ, ORM1, LYN, STMN1 significantly increased in cervical cancer, while LUM, BGN, KRT4 significantly decreased." (PMID 27690342, 2016). "On the other hand, LUM, BGN and KRT4 significantly decreased in cervical cancer samples." (PMID 27690342, 2016).